CXCL14 (C-X-C motif chemokine ligand 14)
Diseases named in the same sentence as CXCL14 in open-access papers (continued):
Sharing a sentence is not in itself a finding about the gene and the disease.
Insulin resistance (11 papers, 2010 to 2025). Increased resistance towards insulin, that is, diminished effectiveness of insulin in reducing blood glucose levels. "In addition, Cxcl14-deficient mice exhibited lower weight, high blood glucose levels due to insulin resistance, and reduced bacterial clearance compared with wild-type mice, although the mice were viable." (PMID 37980373, 2023). "Animal studies have shown that CXCL14 promotes the development of visceral obesity and adipose tissue inflammation, leading to elevated hepatic gluconeogenesis and the development of insulin resistance." (PMID 37835681, 2023). "Increased expression levels of CXCL14 in ≤37 week gestation babies may thus trigger a trajectory towards insulin resistance later in life." (PMID 22808055, 2012). "In adipocytes, pioglitazone and spironolactone induce the expression of C-X-C motif chemokine ligand-14 (CXCL14), a chemokine that is released by BAT and protects against insulin resistance." (PMID 36694227, 2023). "Once systemic insulin resistance is observed in advanced stages of T2DM, the CXCL14 gene may become more active in PCa, resulting in its regression through immune response." (PMID 35399507, 2022). "Recently, findings suggested CXCL14 may protect against insulin resistance by promoting the recruitment of non-inflammatory macrophages to adipose tissues, thereby supporting brown fat activity." (PMID 41187617, 2025). "C-X-C motif chemokine ligand 14 (CXCL14), which is required for the activation of dendritic cells, is another chemoattractant participates in the recruitment of macrophages into adipose tissue and insulin resistance, although its receptor has not yet been identified." (PMID 36119080, 2022).
colon carcinoma (10 papers, 2019 to 2026). "Our results showed that CXCL14 was mainly expressed in fibroblasts, making it an underlying potential target for colon cancer." (PMID 37563546, 2023). "Additionally, consistent with our findings, low levels of CXCL14 in bulk cancer tissue were reported to be linked to poor survival rates in colon cancer." (PMID 40759242, 2025). "Decreased CXCL14 expression indicates a poor prognosis and causes metastasis in colon cancer." (PMID 33167940, 2020). "Also, CXCL14 was identified as an underlying therapeutic target for colon cancer." (PMID 37563546, 2023). "Our findings highlight CXCL14's potential to enhance anti-tumor immunity and provide new insights into its therapeutic applications in colon cancer." (PMID 42193871, 2026). "In conclusion, CXCL14 inhibits colon cancer progression by modulating both tumor cell behavior and the immune landscape, making it a promising candidate for targeted immunotherapy." (PMID 42193871, 2026). "Our results demonstrate that CXCL14 suppresses colon cancer cell proliferation, migration, and metastasis." (PMID 42193871, 2026). "This study investigates the functional impact of CXCL14 on colon cancer by exploring its effects on tumor cell behavior and the immune microenvironment." (PMID 42193871, 2026). "This suggests that CXCL14 silencing plays an important role in the process of colon cancer metastasis, as mentioned in a previous study." (PMID 39409185, 2024). "Then, the single-cell analysis, biological enrichment, immune infiltration and drug sensitivity analysis were performed to illustrate the role of CXCL14 in colon cancer, which enriched its regulatory effect in cancers." (PMID 37563546, 2023). "In this paper, we analyzed the expression profiles of multiple human clinical colon cancer datasets and mouse colon cancer models to reveal the variation trend of CXCL14 expression during colitis, colon polyps, primary colon cancer, and liver metastases." (PMID 38003215, 2023). "Our result found that the CXCL14 was mainly expressed in fibroblasts in the colon cancer microenvironment." (PMID 37563546, 2023). "Based on the data from TCGA-COAD and GTEx database, we noticed a higher RNA level of CXCL14 in colon cancer compared to the normal tissue." (PMID 37563546, 2023). "Secondly, although our research has enriched the regulatory network of CXCL14 in colon cancer, further biological research is still needed." (PMID 37563546, 2023). "Our study identified CXCL14 as a protective factor in colon cancer, which is mainly expressed in fibroblasts." (PMID 37563546, 2023). "In our study, we comprehensively explored the role of CXCL14 in colon cancer, indicating that the CXCL14, as a key factor involved in the liver metastasis process, was mainly expressed in fibroblasts and affected cancer progression through multiple manners." (PMID 37563546, 2023). "Based on the open-accessed data of CRC_EMTAB8107 and CRC_GSE166655, we investigated the gene expression pattern of CXCL14 in the colon cancer microenvironment." (PMID 37563546, 2023). "CXCL14 is highly expressed in colon epithelial cells and shows obvious gene silencing in clinical colon cancer samples, suggesting that its silencing is related to the immune escape of cancer cells." (PMID 38003215, 2023). "CXCL16 mRNA was expressed in 5/5 colon cancer cell lines while CXCL14 was expressed significantly in only one." (PMID 31752131, 2019). "Further, the clinical role of CXCL14 in colon cancer was also explored." (PMID 37563546, 2023). "Following, we tried to explore the biological effect of CXCL14 exerting in colon cancer." (PMID 37563546, 2023). "Reversing the hypermethylation of CXCL14 may be an epigenetic therapy for colon cancer." (PMID 38003215, 2023). "We generated stable cell lines overexpressing CXCL14 in mouse MC38 and CT26 cells and human HCT15 colon cancer cells, and used these models to assess tumor growth, invasion, and immune cell infiltration." (PMID 42193871, 2026).
colon carcinoma (continued). "Gene profiling of single cells revealed that RGS5-expressing myofibroblasts, CXCL14-expressing fibroblasts and HHIP+ myofibroblasts showed extensive upregulation of extracellular matrix genes, including collagen genes, in colon cancer tissues." (PMID 36463319, 2022). "CXCL14 and CXCL16 mRNA levels and protein expression were significantly higher in colon cancer primary tumors compared to apparently normal colon tissue." (PMID 31752131, 2019). "The median expression levels of CXCL14 and CXCL16 mRNA in primary colon tumors (n = 32) were 13 and five times higher than the median expression levels in normal colon tissue (n = 30), respectively." (PMID 31752131, 2019). "The result showed that the CXCL14 is a protective factor against colon cancer independent of other clinical parameters like age, gender, clinical stage, and TNM classifications." (PMID 37563546, 2023). "CXCL14+ADAMDEC1+ fibroblast can be further divided into three subgroups (ADAMDEC1+CCL13hi, ADAMDEC1+FABP4hi, ADAMDEC1+SFRP1hi), all of which were significantly reduced in colon cancer tissue." (PMID 36463319, 2022). "CXCL16, but not CXCL14, mRNA levels were significantly higher in hematoxylin and eosin positive (H&E(+)) compared to H&E(−) colon cancer lymph nodes or control nodes (P < 0.0001)." (PMID 31752131, 2019). "We investigated the expression of CXCL14 and CXCL16 in colon cancer." (PMID 31752131, 2019).
atherosclerosis (9 papers, 2016 to 2025). A disease characterized by the build-up of fatty material and calcium deposition in the arterial wall resulting in partial or complete occlusion of the arterial lumen. "CXCL14 was upregulated in MF-derived foam cells, and CXCL14 peptide-induced immunotherapy suppresses atherosclerosis in Apoe–/– mice, suggesting a proatherogenic role of CXCL14." (PMID 36602878, 2023). "Additionally, geniposide, a clearing Fire herb with homology of medicine and food, can increase CXCL14 expression in perivascular adipose tissue and induces M2 polarization of plaque macrophages, slowing atherosclerosis progression in mice." (PMID 40061953, 2025). "These proinflammatory and angiostatic properties of CXCL14 taken together may foster progression of atherosclerosis, eventually leading to CAD, and also hinder functional recovery of the affected myocardium following ischemia-reperfusion injury by retarding angiogenesis." (PMID 37255851, 2023). "Interaction between C-X-C motif chemokine ligand 14 (CXCL14) and CXCR4 was found to promote monocyte and platelet migration, and it is involved in thrombus formation, whereas CXCR4 deficient in platelets interrupts the interaction, offering a novel therapeutic strategy for atherosclerosis treatment." (PMID 34445123, 2021). "ST analysis showed that IGF-1 suppressed FOS/FOSB factors and gene expression of MMP9 and CXCL14 in plaque macrophages, suggesting possible involvement of these molecules in IGF-1’s effect on atherosclerosis." (PMID 36602878, 2023). "ST analysis revealed that IGF‐1 inhibited gene expression of FOS/FOSB factors, as well as MMP9 and CXCL14 in plaque macrophages, these molecules may be involved in the IGF‐1 effect on atherosclerosis." (PMID 40156163, 2025).
glioblastoma (8 papers, 2015 to 2026). The most malignant astrocytic tumor (WHO grade IV). "In glioblastoma, CXCL14 in glioblastoma-associated stromal cells could induce glycolysis and invasion of glioma cells by regulating the UCA1/miR-182/PFKFB2 axis." (PMID 32083005, 2020). "In glioblastoma, however, others and us showed that CXCL14 mRNA expression is enriched in tumor samples, where this chemokine is likely produced and secreted in the tumor microenvironment by reactive astrocytes or other types of stromal cells." (PMID 31117166, 2019). "Altogether, these observations point to CXCL14 expression correlating with the most aggressive types of glioblastomas and to the most aggressive regions in the tumor mass, those that drive the growth and dissemination of the tumor in the affected brain." (PMID 31117166, 2019). "We also analyzed several human glioblastoma datasets for CXCL14 expression, and studied if and how it correlates with some of the main clinical aspects of these tumors." (PMID 31117166, 2019). "In order to establish a source of secreted CXCL14 to be used in in vitro experiments with glioblastoma cells, we took advantage of a cell line of NIH-3T3 fibroblasts stably expressing human CXCL14, NIH-CXCL14." (PMID 31117166, 2019). "In fact, in the absence of commercially available bona fide anti-CXCL14 blocking antibodies, we cannot discriminate between a purely direct and a partly indirect mechanism of action for CXCL14 on glioblastoma cells." (PMID 31117166, 2019). "In glioblastoma, we previously showed that CXCL14 mRNA expression is higher than in healthy white matter." (PMID 31117166, 2019). "In our work however, we also show that CXCL14 produced directly by stably overexpressing glioblastoma cell lines, enhances their proliferation and migration ability." (PMID 31117166, 2019). "We also found strong evidence of a subtype-specific enrichment of CXCL14 expression in glioblastoma." (PMID 31117166, 2019). "The objective of our present work is to deepen our comprehension of CXCL14 expression and function in glioblastoma cells." (PMID 31117166, 2019). "To this aim, we performed a series of in vitro experiments to assess if an exogenous source of CXCL14 can affect key properties of glioblastoma cell lines and stem cells." (PMID 31117166, 2019). "Further important issues that need to be addressed are the identification of its receptor in glioblastoma and the production of blocking molecules for both CXCL14 and its receptor, in order to selectively prevent its function." (PMID 31117166, 2019). "We also provide evidence that CXCL14 enhances the sphere-forming ability of glioblastoma stem cells, considered the initiating cells, and is responsible for tumor onset, growth and recurrence." (PMID 31117166, 2019). "In order to set up our in vitro model, we started by measuring CXCL14 expression in a number of human glioblastoma cell lines, and compared them with cultured human astrocytes." (PMID 31117166, 2019). "However, CXCL14 expression is higher in glioblastoma tissues than in surrounding healthy tissues, and CXCL14 enhances the migration and proliferation of glioblastoma cells." (PMID 34789307, 2021). "What Sjöberg and co-authors show however, may be still highly relevant to glioblastoma too, as the exogenous source of CXCL14 they use is the same as ours, i.e., murine fibroblasts ectopically overexpressing human CXCL14." (PMID 31117166, 2019). "This suggests that CXCL14 expression may discriminate, among proneural glioblastomas, those with the worst prognosis." (PMID 31117166, 2019). "Thus, we cannot exclude that in glioblastoma too, CXCL14 exerts its pro-tumoral role at least in part indirectly, by inducing, in the producer cells of the microenvironment, the secretion of other molecules." (PMID 31117166, 2019).
glioblastoma (continued). "Here, we show that indeed CXCL14, both exogenously supplemented and endogenously overexpressed, enhances the proliferation and the migratory ability of two different cell lines of human glioblastoma." (PMID 31117166, 2019). "In support of our previous findings about the enriched expression of CXCL14 in astrocytes in the bulk of the tumor, we found that the cell extracts of cultured human astrocytes contain CXCL14 at a concentration which is at least one order of magnitude higher than that measured in glioblastoma cells." (PMID 31117166, 2019). "In order to extend the frame of our functional observations about CXCL14 possible roles in glioblastoma, we measured the ability of three distinct glioblastoma stem cell lines to form spheres in the presence of NIH-CXCL14 conditioned medium." (PMID 31117166, 2019). "Moreover, our observation that CXCL14 enhances the ability of glioblastoma stem cells to form neurospheres is completely new, and indicates that this chemokine may contribute to key functions of the cells at the origin of glioblastoma." (PMID 31117166, 2019). "Altogether, our results highlight the involvement of CXCL14 in glioblastoma environment, where it likely affects not only established tumor cells, but also the stem cells." (PMID 31117166, 2019). "With the aim of understanding if CXCL14 functional effects we observed on glioblastoma cell lines may be mediated by CXCR4, we employed the specific CXCR4 inhibitor AMD3100 in proliferation assays of U87MG cells incubated with NIH-CXCL14 conditioned medium." (PMID 31117166, 2019). "In the glioblastoma cells we are studying here, though, we do not deem it likely that CXCL14 functions are mediated by ACKR2, as the expression of its mRNA, that we measured by qRTPCR, was undetectable in both U87MG and LN229 cells (not shown)." (PMID 31117166, 2019). "In our model, it is unlikely that CXCR4 is involved, as the specific inhibition of this receptor did not modify CXCL14 effects on glioblastoma cells." (PMID 31117166, 2019). "In the cell extracts of three human glioblastoma cell lines, namely A172, LN229 and U87MG, we could detect, by ELISA, CXCL14 levels in the range of 90–400 pg/mL." (PMID 31117166, 2019).
lymph node metastasis (8 papers, 2013 to 2023). "Altogether, our study demonstrates that high CXCL14 expression is associated with increased lymph node metastasis and worse prognosis in patients with OC." (PMID 34789307, 2021). "By univariate analysis, clinical factors including age, lymph node metastasis and CXCL14 expression were significantly correlated with overall survival." (PMID 23294544, 2013). "Also, the expression of CXCL14 was highly correlated with pathological stages, lymph node metastasis, and angiolymphatic invasion of patients with PC." (PMID 35669852, 2022). "Patients with high lymph-node metastasis showed significantly decreased CXCL14 expression levels." (PMID 36012586, 2022). "Of the 226 CXCL14-positive CRC cases, 8 were in Stage I (submucosa invasion), 83 in Stage II (subserosal invasion), 127 in Stage III (lymph node metastasis) and 8 in Stage IV (distant metastasis); and 57 were well-differentiated, 140 moderately and 29 poorly differentiated." (PMID 23294544, 2013). "CXCL14 and TGFβ1 were not correlated with lymph node metastasis, staging, or overall survival." (PMID 34167551, 2021).
head and neck cancer (7 papers, 2012 to 2023). A primary or metastatic malignant neoplasm affecting the head and neck. "In addition, CXCL14 suppresses human papillomavirus-associated head and neck cancer through up-regulation of MHC-1 expression and antigen-specific CD8T cell response." (PMID 34631695, 2021). "Interestingly, CXCL14 expression has been associated with reactive oxygen species, whereby downregulation of CXCL14 leads to a stimulation of angiogenesis in head and neck cancer." (PMID 22808055, 2012). "In colorectal, head and neck cancers and hepatocellular cell carcinoma, CXCL14 suppresses tumor progression and is correlated with better survival." (PMID 35769715, 2022). "It has been found that CXCL14 is significantly down-regulated in HPV-positive head/neck cancer and cervical tissue specimens, and restoring the expression of CXCL14 in oropharyngeal cancer cells could clear tumors in mice." (PMID 37835641, 2023).
gastric cancer (6 papers, 2014 to 2023). A primary or metastatic malignant neoplasm involving the stomach. "Supporting this, epigenetic silencing of CXCL14 has been found to promote progression of breast, colorectal as well as gastric cancer." (PMID 27899617, 2017).
hepatocellular carcinoma (6 papers, 2013 to 2024). A malignant tumor that arises from hepatocytes. "Using antibody arrays, CXCL14 has been identified as a potential diagnostic marker of hepatocellular carcinoma." (PMID 23294544, 2013). "CXCL14 overexpression inhibits angiogenesis, proliferation, invasion, and migration of hepatocellular carcinoma cells." (PMID 36012586, 2022). "Likewise, increased levels of CXCL10, CXCL12, and CXCL14 in hepatocellular carcinoma patients correlated with favorable survival rates." (PMID 38275602, 2024). "Finally, the exogenous addition of CXCL14 inhibited the activity, clonal formation and migration of hepatoma cells (HepG2)." (PMID 37835641, 2023). "In addition, some studies also found that CXCL14 was significantly down-regulated in HBV-related hepatocellular carcinoma tissues." (PMID 37835641, 2023).
osteosarcoma (6 papers, 2016 to 2025). A usually aggressive malignant bone-forming mesenchymal neoplasm, predominantly affecting adolescents and young adults. "In osteosarcoma, activation of Iroquois homeobox 1 (IRX1), as a prometastatic protein, directly increases CXCL14 expression, and promotes osteosarcoma metastatic activity via elevated CXCL14/NF-κB signaling." (PMID 26733763, 2016). "Osteosarcoma had 25 significant relationships, notably including IL-4/IL-1β (r2 = 0.58, p = 0.000048), IL-12 p40/IL-4 (r2 = 0.47, p = 0.0015), CXCL5/IL-27 (r2 = −0.48, p = 0.001), CXCL14/IL-15 (r2 = 0.66, p = 0.0000021)." (PMID 41008853, 2025).
Arthritis (5 papers, 2016 to 2024). Inflammation of a joint. "It was clear that T cells proliferated in the synovial tissue of PsA mice and enhanced arthritis by producing CXCL14 and IL-32, which likely exacerbated local and systemic inflammation." (PMID 39114979, 2024). "CXCL14 is significantly upregulated in inflamed joints of collagen-induced arthritis and its overexpression exacerbates arthritis in a mouse model, which is in line with the studies carried out in patients with rheumatoid arthritis." (PMID 26733763, 2016). "The neuroinflammatory role of CXCL14 is not well understood, but its overexpression exacerbates collagen-induced arthritis, and its addition to dendritic cells results in increased NF-κB activity and their activation, suggesting its involvement in inflammatory responses." (PMID 38997748, 2024). "Notably, synovial fibroblasts were recently shown to drive the local inflammatory tissue priming in preclinical models of arthritis in a C3-dependent manner; the primed fibroblast appeared to upregulate both C3 and CXCL14 mRNA expression." (PMID 38832018, 2024).